IL6 (interleukin 6)
Diseases named in the same sentence as IL6 in open-access papers (continued):
Sharing a sentence is not in itself a finding about the gene and the disease.
colitis (continued). "Additionally, certain E. faecalis strains have been reported to reduce expression of pro-inflammatory cytokines such as TNF-α and IL-6, which drive neutrophil-mediated inflammation in colitis models." (PMID 41472066, 2025). "The untreated acetic acid-induced colitis rats presented increased serum IL-6 and TNF-α." (PMID 40430512, 2025). "Many studies have shown that CB or AKK can play a protective role in mouse colitis by regulating some key components related to the inflammatory response, such as pro-inflammatory cytokines (IL-1β, IL-6, and TNF-α) and anti-inflammatory cytokines (IL-4 and IL-10)." (PMID 39840995, 2025). "The in vitro treatment of colonic biopsies from DSS-induced colitis mice with RvD2 (0.01, 0.1, and 0.3 μM) or anti-TNFα resulted in a significant downregulation of the pro-inflammatory cytokine transcripts TNFα and IL6, suggesting a marked attenuation of colonic inflammation." (PMID 40649782, 2025). "Similarly, L15 exerts anti-inflammatory effects in colitis by suppressing LPS-induced NF-κB activation and lowering IL-6 and TNF-α levels." (PMID 41141596, 2025). "In models of acute or systemic inflammation, including carrageenan-induced pleurisy, nociception and paw edema, and DSS-induced colitis, treatment decreased leukocyte migration, Th1/Th17 polarization, levels of pro-inflammatory cytokines (IL-6, TNF-α, IFN-γ) and increased IL-10." (PMID 41470797, 2025). "miR-93-5p, an IL-6-driven G-MDSC exosome, promotes the differentiation of M-MDSCs into M2 macrophages and is implicated in the STAT3 signaling mechanism that promotes the transition from colitis to cancer." (PMID 39990210, 2025). "In addition, the SOD inhibition rate and interleukin-6 levels were lower in the bet15+colitis group than in the colitis group." (PMID 41515203, 2025). "In line with our hypothesis, it has been shown that Nrf2 prevents LPS-induced transcriptional upregulation of several pro-inflammatory cytokines, such as IL-6 and IL-1β, whose production is increased in Nrf2−/− mice with dextran sulfate-induced colitis." (PMID 40002358, 2025). "Our study showed that PA improved colitis in mice, as evidenced by improvements in disease-related indicators, including weight loss, DAI scores, pathological manifestations, and levels of pro-inflammatory mediators (IL-1β, IL-6, TNF-α)." (PMID 40969742, 2025). "Supplementation with Hydroxyproline could attenuate dextran sulfate sodium-induced colitis in mice by inhibiting the NF-кB/IL-6." (PMID 40573066, 2025). "Similarly, indole-3-carbinol (an indole resulting from the hydrolysis of glucobrassicin) was able to significantly decrease the intestinal expression of NF-κB and several inflammatory factors such as TNF-α, IL-1β, IL-6, and IL-8 in mice with colitis." (PMID 40508374, 2025). "For example, A. finegoldii administration demonstrated marked efficacy in symptom amelioration within the DSS-induced colitis murine model, but it may also promote right-sided colon cancer through the IL-6/STAT3 pathway." (PMID 40509521, 2025). "In fact, patients with colitis had elevated levels of IL-1β, IL-6, and TNF-α." (PMID 40238292, 2025). "Furthermore, Lipoxin A4 and its analogs can alleviate colitis, reduce adipose tissue inflammation, and regulate the secretion of chemokines (IL-6, IL-8)." (PMID 39852383, 2025). "Moreover, Sphingomonas, another microorganism positively associated with IL-6 and TNF-α in our study, was identified as more abundant in the gut of patients with colitis-associated cancer and in an inflammation-associated animal model." (PMID 41154794, 2025). "Sini decoction inhibits the onset and progression of colitis-associated colon cancer in mice by upregulating the numbers of A. muciniphila, Bifidobacterium in the intestine, and CD8+ T cells, while downregulating CD4+ T cells, IL-6, and TNF-α." (PMID 40028328, 2025).
colitis (continued). "Furthermore, they exhibit immunomodulatory effects by suppressing pro-inflammatory cytokines such as TNF-α and IL-6 in LPS-stimulated macrophages and colitis-induced mice." (PMID 40509414, 2025). "Rutin can decrease IL-6 levels in experimental animals induced with colitis." (PMID 40395731, 2025). "After gavage with DSS in piglets, compared with those in the CT group, the serum levels of IL-6 and IL-8 significantly increased (p < 0.05), whereas the level of IL-10 significantly decreased (p < 0.05), indicating that the colitis model in piglets was successfully established." (PMID 40362046, 2025). "Similarly, in a study involving mice with DSS-induced colitis, Bifidobacterium pseudolongum was found to reduce the mRNA expression levels of pro-inflammatory cytokines (IL-1β, IL-6, IL-10, and TNF-α)." (PMID 40299512, 2025). "By suppressing this pathway, MP may reduce the production of pro-inflammatory cytokines, such as IL-1β, TNF-α, and IL-6, thereby alleviating colitis symptoms." (PMID 40012624, 2025). "Notably, colitis mice exhibited increased serum IL-6 and colonic TNF-α concentrations in contrast with the CON group." (PMID 39857378, 2025). "Indeed, it has been demonstrated in the literature that α-linolenic acid can reduce the inflammatory state of colitis by down-regulating the mRNA levels of several pro-inflammatory genes, such as IL-6, cyclooxygenase 2, and tumor necrosis factor α." (PMID 40286023, 2025). "Interleukin 6 and IL-1β play vital roles in the pathophysiology of inflammatory diseases by accelerating neutrophil recruitment and inhibiting T cell differentiation, which are used to monitor the occurrence and development of colitis." (PMID 40431130, 2025). "Indeed, our recent study showed that Compound-23 treatment decreased the intestinal IL-6 expression in the mice model of DSS-induced colitis." (PMID 40563351, 2025). "Therefore, the regulatory effect of IA-0130 on the IL-6 signaling pathway in DSS-induced colitis conditions was evaluated." (PMID 38916850, 2024). "Additionally, at a dose of 40 mg/kg, sinapic acid demonstrated a significant decline in mean TNF-α and IL-6 levels in mice with acetic acid-induced colitis." (PMID 38732594, 2024). "This study showed that both OBB and BBR can increase the abundance of Bacteroides, and OBB has superior anti-colitis activities, including improving the intestinal mucosal barrier, inhibiting colitis tissue damage, and reducing pro-inflammatory factors such as IL-6, IL-1β, IL-17, TNF-α and IFN-γ." (PMID 38660314, 2024). "There was also a reduction in the expression of IL-6 compared to colitis recovered naturally." (PMID 39069899, 2024). "Compared with the model group, different concentrations of oat and bran treatment groups could promote the expression of IL-10 and inhibit the gene expression of IL-6 and TNF-α, thus mitigating the mucosal damage caused by DSS-induced colitis." (PMID 39770986, 2024). "Importantly, EEN treatment eliminated mechanical stress and attenuated IL-6 up-regulation and the Th17 immune response in rats with CD-like colitis." (PMID 38337648, 2024). "However, we did observe higher expression of key inflammatory cytokines (Il6, Il1b, Il17b) and chemokines (Cxcl1 and Cxcl2) involved in colitis in wild-type compared to R38E-PAR2 mice." (PMID 39171684, 2024). "DHA administration significantly decreased the IL-6 level compared to the colitis group." (PMID 39105785, 2024). "This study found that compared with colitis models induced by DSS, expression levels of NO, TNF-α, IL-1β, and IL-6 were remarkably reduced in the peripheral blood and colon tissues of colitis mice pre-treated by B. tequilensis YB-2, while expression levels of IL-10 and IL-4 significantly increased." (PMID 38998101, 2024).
colitis (continued). "After measuring the levels of pro-inflammatory cytokines in the serum of each group of mice, we found that compared to the control group, the levels of TNF-α (p < 0.001), IL-1β (p < 0.01), and IL-6 (p < 0.05) were significantly increased in the serum of mice with DSS-induced colitis." (PMID 38474831, 2024). "Another study found that oral administration of probiotic-fermented red ginseng could significantly relieve the symptoms of colitis in (DSS)-induced mouse mode through downregulating the serum levels of inflammatory factors (IL-6 and TNF-α)." (PMID 38698858, 2024). "A previous study showed that IL-6 levels were elevated in a DSS-induced colitis model mice." (PMID 38504172, 2024). "DH effectively suppressed the levels of IL-6 induced in response to colitis compared to CP." (PMID 38539873, 2024). "TNF-α, IL-6, and IL-1β are highly expressed in experimental mice colitis." (PMID 39148547, 2024). "Additionally, IL-6, a cytokine essential to the differentiation of naïve T cells into Th17 cells, is upregulated in the colonic tissues of colitis-irAE patients compared to normal tissues." (PMID 39247203, 2024). "The decreased gonadal T level found in our rats with colitis may be related to increased inflammatory markers, such as IL-6." (PMID 39125425, 2024). "Moreover, we evaluated the main pro-inflammatory cytokines (i.e., IL-1β and IL-6) involved in colitis." (PMID 38542183, 2024). "Additionally, studies have revealed that the crosstalk between the Wnt and inflammatory signaling pathways mediates the production of inflammatory cytokines, such as IL-6 and IL-8, during the pathogenesis of colitis." (PMID 38491161, 2024). "In addition, black tea inhibited inflammatory cytokines including IL-12, IL-23, IL-6, and IL-1β, and suppressed IκBα phosphorylation and activity of NF-κB in an LPS-induced colitis model." (PMID 39572022, 2024). "Butein, a major constituent of Toxicodendron vernicifluum ameliorated colitis in IL-10(-/-) mice by reducing the colonic inflammatory score by > 50%, reducing the expression levels of IL-6, IL-1β, IFN-γ pSTAT3 and MMP-9, also inhibiting IL-6-induced activation of STAT3 in Colo 205 cells." (PMID 39494333, 2024). "Furthermore, LM-CsA NPs significantly decreased the expression of inflammatory factors such as TNF-α and IL-6 and increased the expression of gut barrier-related proteins such as E-cadherin, ZO-1, and occludin protein in colitis mice." (PMID 39512421, 2024). "During colitis, the release of several proinflammatory mediators, such as IL-6, IL-18, IL-22, and RELMβ, has been shown to enhance the intestinal epithelial cells proliferation, induce the release of antimicrobial peptides and anti-inflammatory mediators and promote the mucosa wound healing." (PMID 39684467, 2024). "Mice with DSS-induced colitis exhibited significantly elevated levels of IL-6, TNF-α, and IL-1β." (PMID 39296302, 2024). "Furthermore, it has been shown that the activation of AHR by various endogenous ligands inhibits the NF-κB signaling pathway, reducing the expression of IL-1β and IL-6 in conditions such as periodontitis, bronchitis, and colitis." (PMID 39465158, 2024). "Similarly, Aronia berry extract, rich in phenolic acids and anthocyanins, lowered IL-6 levels in DSS-induced colitis in mice." (PMID 37049797, 2023). "Previous studies also showed that MCFA could significantly reduce the level of proinflammatory cytokines, such as IL-6 and IL-1, and relieve the inflammation of colitis in rats." (PMID 36397688, 2023). "To further understand the protective efficacy of PS, we analyzed the content of colitis-associated inflammatory cytokines and found that pretreatment with PS reduced the levels of pro-inflammatory cytokines, such as IL-1β, TNF-α, and IL-6, while increased anti-inflammatory TGF-β1 cytokine levels." (PMID 37447380, 2023).
colitis (continued). "To investigate the effect of BFO on the inflammatory responses of DSS‐induced colitis mice, we determined the mRNA expression levels colon‐related genes, including IL‐1β, IL‐6, TNF‐α, inducible nitric oxide synthase (iNOS), and cyclooxygenase 2 (COX‐2), by qPCR." (PMID 38018589, 2023). "However, experiments with rat models of colitis demonstrated the prominence of exogenous BMP7 in lowering pro-inflammatory cytokine production (especially IL-6) and thus protecting mucosa." (PMID 37391444, 2023). "The results revealed that L. plantarum, COS, and the synbiotics alleviated the symptoms of mice colitis and inhibited the changes in short-chain fatty acids (SCFAs), tumor necrosis factor-α (TNF-α), interleukin (IL)-1β, IL-6, IL-10, and myeloperoxidase (MPO) caused by DSS." (PMID 37297494, 2023). "Therefore, we measured the proinflammatory cytokine production in colon tissues that DSS-induced acute colitis is accompanied by increased cytokine expression shown by ELISA and qRT-PCR, including IL-6, IL-1β and IL-17." (PMID 37143672, 2023). "Finally, PR1P prevented weight loss and tissue injury and reduced plasma levels of key inflammatory cytokines IL-1β and IL-6 in a rat TNBS-induced colitis model." (PMID 37187742, 2023). "Moreover, level of IL-6, an important indicator for colitis progression, was significantly elevated in colitis." (PMID 37723551, 2023). "Similarly, genes involved in proliferation and differentiation (e.g., Cyclin D1, p21), pro-apoptosis (e.g., Bax, Bak, caspase-3), and inflammation (e.g., iNOS, IL-6); previously shown to be regulated by VitD, were altered in HF-fed mice with colitis/CAC." (PMID 36768196, 2023). "Infectious diseases related to the cause of colitis cytokine activate the protective response of immune cells such as macrophages, neutrophils, and lymphocytes in the colonic mucosa and induce TNF-α, IFN-γ, IL-6, and other immune cells." (PMID 37834221, 2023). "The colon’s TNF-α, IL-6, and IL-1β expressions were raised in experimental colitis." (PMID 37646040, 2023). "In addition, in dextran sulfate sodium-induced colitis mice, Bifidobacterium not only downregulated levels of IL-6 and TNF-α, but also upregulated level of IL-10." (PMID 35918555, 2023). "Similarly, colonic pro-inflammatory cytokines (TNFa and IL-6) in Parkin-/- mice were lower in WT mice with DSS-induced colitis." (PMID 37056928, 2023). "Moreover, another study also showed that vitamin E treatment on rats with colitis brought on by DSS had decreased the level of pro-inflammatory IL-6." (PMID 37834115, 2023). "However, FMT failed to rescue the percentage of weight loss and the mRNA levels of Tnf-α, Il-1β, and Il-6, suggesting that intestinal microbiota is involved in the development of DSS colitis." (PMID 37813835, 2023). "Seven hub genes IL10, IL4, IL6, IFNG, IL1B, TNF and IL17A might be responsible for causing Colitis and Arthritis, except for Rheumatoid Arthritis." (PMID 36989283, 2023). "We observed elevated expression of Il6 in whole lung tissue of TCRδ-/- mice with colitis." (PMID 37063825, 2023). "Therefore, we assessed the effects of OPs on inflammation and oxidative stress in mice with colitis by measuring the levels of inflammatory markers (IL-6, IL-1β, TNF-α) and redox markers (MDA, SOD, T-AOC) in serum and colonic tissues." (PMID 38140314, 2023). "Thus, there is the potential for the expanding population of activated neutrophils and macrophages in the lungs of TCRδ-/- mice after DSS-induced colitis to express and secrete IL-6 and elicit further immune responses." (PMID 37063825, 2023). "Deletion of 5-HT2B from the mouse model of chemically induced colitis leads to an increased level of IL-6 and an accompanying upregulation of STAT3 activation, which boosts the survival and proliferation of intestinal epithelial cells during inflammation, leading to cancer initiation." (PMID 38106420, 2023).
colitis (continued). "However, it is still unclear if Blautia is effective for treating colitis because it helps to enhance the creation of SCFAs, while is concentrated in UC patients’ gut and positively correlates with IL-1β, IL-6, and TNF-α." (PMID 37297494, 2023). "However, treatment with RG or fRG suppressed UCDF-induced myeloperoxidase, TNF-α, and IL-6 expression, and NF-κB+CD11c+ cell number, leading to the amelioration of colitis." (PMID 36926604, 2023). "In the preventive trial with DSS-colitis, dexamethasone-induced an increase in Hif1a and Il6, and a decrease in Tjp1 expression compared to controls, while Tgfb1 and Vegfa expression was increased in the MTADV group, as well as Nos2 and Tjp1 in comparison to dexamethasone." (PMID 37047397, 2023). "Concretely, PTSO was tested in two experimental models of colitis, which were associated with the regulation of cytokines in inflamed colonic tissue, leading to a reduction of pro-inflammatory cytokines IL-1β, TNF-α, and IL-6." (PMID 36986093, 2023). "In a murine model of colitis, the previous and during-induction administration of CC-AST relieves colitis and significantly inhibits the expression of the inflammatory markers IL-1β, IL-6, TNF-α, cyclooxygenase-2, myeloperoxidase (MPO), iNOS, and NO in a more potent way than free AST." (PMID 37514016, 2023). "According to the results, VK2 restored the colon lengths, improved the colonic histopathology, reduced the levels of proinflammatory cytokines (such as IL-1β, TNF-α, and IL-6), and boosted the level of the immunosuppressive cytokine IL-10 in the colon tissues of the colitis mice." (PMID 36769323, 2023). "However, these mice are hypersensitive to DSS colitis with defective mucosal repair and increased colonic caspase 3 cleavage and IL6 mRNA expression." (PMID 38268707, 2023). "Additionally, they have been shown to modulate the expression of anti- and pro-inflammatory cytokines in the colon and plasma of colitis models and have a higher ability to suppress IL-6 and increase IL-10 levels than wild-type probiotics." (PMID 37049407, 2023). "Studies have shown that increased levels of S1P were detected in the SPHK2 knockout mice, which exacerbates chronic intestinal inflammation, and through S1PR1–NF-κB-IL-6 (interleukin-6)–STAT3 (activator of transcription factor 3) signal leads to the development of colitis related cancers." (PMID 37305043, 2023). "In turn, both the single anthocyanin compounds (cyanidin, cyanidin glycosides, pelargonidin) and anthocyanin-rich extract alleviated the clinical symptoms of colitis, decreasing the expression of IL-6 and increasing the expression of Foxp3 in the colon tissues, and promoting Treg cell expansion." (PMID 37049797, 2023). "The expression of CRP, ESR, FC, interleukin-6(IL-6), IL-8 and IL-10 were different between the two groups, and except for IL-4 and IL-12P70, the expression of inflammatory markers was higher in extensive colitis." (PMID 37457023, 2023). "Interestingly, upon colitis induction by DSS or C. rodentium infection, the loss of CLDN3 expression significantly exacerbated the expression of TNF-α and IL-6." (PMID 38010872, 2023). "Furthermore, previous studies revealed that oral gavage of live L. sakei alleviated symptoms and histopathology of colitis and reduced the expressions of pro-inflammatory cytokines (TNF-α, IL-1 and IL-6) in the colons of DSS-induced colitis animals." (PMID 36986118, 2023). "It has been observed that IL-6 can induce the phosphorylation of STAT3, and the upregulation of phosphorylated STAT3 is implicated in the pathogenesis of colitis, emphasizing the critical role of STAT3 in colitis development." (PMID 37375369, 2023). "Unlike TNF-α and IL-6, high serum levels of IL-17 at baseline have been associated with severe colitis in patients on ipilimumab." (PMID 36900420, 2023). "Elevated production of inflammatory cytokines, such as TNF-α, IL-1β, and IL-6, could injure gut epithelia cells and exacerbate colitis." (PMID 37324477, 2023).